TREM2 (triggering receptor expressed on myeloid cells 2)
Diseases named in the same sentence as TREM2 in open-access papers (continued):
Sharing a sentence is not in itself a finding about the gene and the disease.
liver fibrosis (21 papers, 2019 to 2025). "Only very recently, Hendrikx and colleagues were able to show that TREM2+ macrophages are implicated in hepatic fibrosis and that loss of Trem2 aggravated murine MCD-induced NASH." (PMID 36766683, 2023). "In line with this, loss of Trem2 resulted in an increased pro-inflammatory response, which ultimately aggravated liver fibrosis in murine models of NAFLD." (PMID 36766683, 2023). "In sum, these data suggest that loss of Trem2 results in an altered immune response, most likely contributing to higher liver fibrosis during the progression of NAFLD." (PMID 36766683, 2023). "TREM2 can inhibit chronic inflammation and protect the liver from injury caused by some pathological changes, like hepatic fibrosis or cirrhosis, viral hepatitis, nonalcoholic fatty liver, and HCC." (PMID 35047095, 2022). "In liver cirrhosis, the scar-associated macrophages, which were defined as TREM2+CD9+ macrophages, differentiated from circulating monocytes and expanded in liver fibrosis." (PMID 37380987, 2023). "It is worth noting that this subpopulation is also classified as pro-fibrotic, as TREM2+CD9+ macrophages expand in liver fibrosis." (PMID 36982747, 2023). "Macrophage, populated in the liver during NAFLD, express a high level of Spp1, Cd9, and Trem2 and participate in hepatic fibrosis." (PMID 37822923, 2023). "The results of this study showed a significant correlation between this profibrotic macrophage subset (CD9+TREM2+ macrophages) and the severity of liver fibrosis in patients with NAFLD." (PMID 37415134, 2023). "Upon TRL injection, hepatic protein levels of the phosphorylated and active form of the stress kinases JNK1 and JNK2, markers of liver fibrosis, were elevated in Trem2−/− mice compared to WT mice." (PMID 36766683, 2023). "These Scar associated macrophages (SAMacs) can be distinguished from other macrophage populations by their high expression of TREM2, CD9, and SPP1, as well as their close physical association with areas of hepatic fibrosis in both mice and humans." (PMID 33574817, 2020). "In mouse models of MASH, LAMs are recruited via an oxidized low-density lipoprotein (oxLDL)–TREM2–rapamycin complex 2 (mTORC2) axis and contribute to the resolution of liver fibrosis in a TREM2 and peroxisome proliferator-activated receptors δ/γ (PPAR-δ/γ) dependent manner." (PMID 41479922, 2025). "Moreover, the deletion of Trem2 resulted in increased weight gain, liver damage and hepatic fibrosis in two different models of NAFLD." (PMID 36766683, 2023). "In addition, using CCl4-induced DBA/2J mouse liver fibrosis model, we found that expression of Trem2 was significantly increased in mice with advanced liver fibrosis." (PMID 37415134, 2023). "However, a recent study highlighted a new role of TREM2 in hepatic fibrosis, which differs from its protective role in inflammation." (PMID 33297569, 2020). "However, in chronic or advanced stages, the upregulation of TREM2 may shift toward a pathological role, contributing to hepatic fibrosis and exacerbating disease severity." (PMID 40636122, 2025). "The increased abundance of these TREM2+ macrophages in murine NASH as well as in murine and human liver fibrosis was further confirmed in other single-cell transcriptomic datasets." (PMID 36766683, 2023). "A study in 2019 identified a subpopulation of profibrotic TREM2+CD9+ macrophages, which had a key role in the progression of liver fibrosis." (PMID 36503486, 2022). "Application of scRNA-seq method, TREM2+CD9+ macrophages and ACKR1+PLVAP+ endothelial cells were identified and expanded in liver fibrosis." (PMID 35791909, 2022). "In this review, we evaluate the function of TREM1 and TREM2 in liver injury, NASH, hepatic fibrosis, and HCC." (PMID 33297569, 2020).
liver fibrosis (continued). "In a separate cohort, we correlated hepatic gene expression levels of TREM2 with plasma ALT levels, as a measure of liver damage, hepatic gene expression levels of COL1A1, as a liver fibrosis marker, and with liver triglyceride (TG) levels, as a marker for hepatic steatosis." (PMID 36766683, 2023). "We also found that T3 could inhibit the profibrotic TREM2+CD9+ macrophage, which had been identified an important player in the progression of liver fibrosis." (PMID 36503486, 2022). "In our study, we found that T3 could inhibit the profibrotic macrophage TREM2+CD9+ macrophage, which had been identified an important player in the progression of liver fibrosis." (PMID 36503486, 2022). "Since TREM2 has disease-related functions in other tissue macrophages, including Microglia and adipose tissue macrophages, unraveling the transcriptional control of this gene program is highly relevant for the study of NAFLD and hepatic fibrosis." (PMID 33574817, 2020).
melanoma (20 papers, 2020 to 2025). A malignant, usually aggressive tumor composed of atypical, neoplastic melanocytes. "In melanoma, single-cell transcriptomic analyses reveal that TREM2 is upregulated on immunosuppressive TAMs associated with immune checkpoint resistance." (PMID 40821795, 2025). "TREM2+ TAMs from ESCC exhibited a consistent expression pattern and identical signature genes (TREM2, SPP1, APOE, C1QC, C1QB, and C1QA) with melanoma cells, suggesting that TREM2+ TAMs were associated with immunotherapy resistance in ESCC." (PMID 37187751, 2023). "To investigate the association of TREM2+ TAMs with immunotherapy resistance, we re-analyzed scRNA-seq data of 48 melanomas (GSE120575) treated with ICB therapy." (PMID 37187751, 2023). "Analysis of 29 bulk-RNA melanoma samples from dataset GSE78220 revealed that a gene signature of 40 genes associated with TREM2+ TAMs was upregulated in the transcriptome of melanomas that did not respond to anti-PD1 therapy." (PMID 37187751, 2023). "Spatial transcriptomics analysis of micro-glial cells near melanoma demonstrates that there is a homeostatic-to-regenerative transition in micro-glial cells that is associated with increased levels of C3, IL-10, and TREM2 and reduced levels of CXCL10 and MHC-II." (PMID 41463339, 2025). "Interestingly, scRNA-seq analysis of melanoma patients treated with immunotherapy demonstrated that TREM2+ TAMs were linked to immunotherapy modulation, which exhibited a similar gene signature to TREM2+ TAMs in ESCC." (PMID 37187751, 2023). "TREM2 is linked to immunotherapy resistance in multiple cancers, including melanoma, where TAMs with high TREM2 expression exhibit immunosuppressive properties." (PMID 40055311, 2025). "On the other hand, emerging evidence reveals that GPNMB+TAMs in melanoma and breast cancer microenvironments exhibit significant upregulation of immunosuppressive markers including TREM2 and CD206." (PMID 41180454, 2025). "TREM2 blockade in murine melanoma models results in enhanced IFN-γ signaling, macrophage repolarization, and a more permissive environment for T cell–mediated tumor clearance." (PMID 40821795, 2025). "When melanoma first enters the brain, it encounters an environment dominated by micro-glial cells, which express the receptors TREM2, CX3CR1, and complement receptors." (PMID 41463339, 2025). "Imaging of lung metastasis from patients with cancer revealed that TREM2+ cells reside at the invasive margin of metastases in both breast cancer and other primary tumor sources such as melanoma and soft-tissue sarcoma." (PMID 37756565, 2023). "Correspondingly, the expression of TREM2 protein is upregulated in Melanoma tissue in the Human Protein Atlas." (PMID 36741909, 2023). "The scRNA-seq analysis in dataset GSE120575 indicated significant enrichment of TREM2+ TAMs in melanoma patients (n=48) with poor immunotherapy response, which had an identical gene signature with TREM2+ TAMs from ESCC." (PMID 37187751, 2023). "IHC of primary carcinomas and melanomas demonstrated co-expression of TREM2 with macrophage markers CD163, CD68, MAF-B, CSF1R, and MITF; however, the study did not specify the types of cancer analyzed." (PMID 36119485, 2022). "We subcutaneously injected B16-F10 melanoma cells into WT mice (CD45.1) engrafted with BMs (CD45.2) from WT or TREM2-TG mice and measured the tumor volume every other day." (PMID 33980160, 2021). "Surprisingly, B16F10 melanoma cells were rarely observed in the lungs of hu-Ig-injected TREM2-TG mice, whereas melanoma cells were apparent in the lungs of TREM2-Ig-injected TREM2-TG mice (19 ± 1, B16F10 cell spots)." (PMID 33980160, 2021). "Notably, CST3 was recently reported as a glucocorticoid response gene and can predict immunotherapy failure of patients with multiple cancers, including melanoma, possibly by directing recruitment of Trem2+ macrophages." (PMID 36969056, 2023).
melanoma (continued). "A previous study on melanoma found that the increased ratio of TREM-1 to TREM-2 may promote the pro-inflammatory and pro-tumor state of the tumor microenvironment." (PMID 34122331, 2021). "Moreover, in melanoma-bearing WT mice, injection of bone marrow cells from TREM2-TG mice exerted greater antitumor effects than that with cells from WT control mice." (PMID 33980160, 2021). "To confirm whether TREM2 affects tumor progression in vivo, we injected TREM2-TG or WT mice with B16F10 melanoma cells after intraperitoneal injection of hu-Ig or TREM2-Ig." (PMID 33980160, 2021). "Several melanomas (large black spots, 14 ± 1) were observed in the lung tissues of WT-BM-recipients (open bars); however, only a few melanomas were detectable (2 ± 1) in lung tissue of TREM2-TG-transplanted mice (solid bars)." (PMID 33980160, 2021). "In murine melanoma models, intertumoral CX3CR1+ CD206+ macrophages expressing TREM2 suppressed vaccine efficacy, a suppression reversed by TREM2-blocking antibodies." (PMID 41303525, 2025). "Microglia that are recruited to the site of melanoma through CSF1R and TREM2 and are exposed to C3 adopt a supportive phenotype characterized by IL-10 and TGF-β release, extracellular matrix remodeling, synaptic pruning, and reduction in cytotoxic signals." (PMID 41463339, 2025). "We also observed that TREM2+ TAMs from ESCC and melanomas were clustered together, suggesting a consistent expression pattern of TREM2+ TAMs between ESCC and melanomas." (PMID 37187751, 2023). "To validate the differences in gene expression patterns of TREM2+ TAMs between ESCC and melanomas, we extracted the macrophages from the two tumors and integrated them into a shared dimensional space." (PMID 37187751, 2023). "As expected, TREM2+ TAMs from ESCC specifically expressed TREM2, SPP1, APOE, and three complement genes, consistent with TREM2+ TAMs from melanomas." (PMID 37187751, 2023). "TREM2-TG mice showed a significantly lower tumor volume and rare metastatic tumor spots compared with WT mice when they were injected with B16F10 melanoma cells." (PMID 33980160, 2021). "The tumor volume in TREM2-overexpressing transgenic (TREM2-TG) B16F10 melanoma mice was significantly smaller than that in WT mice, suggesting that TREM2 activation can enhance the killing of melanoma cells by promoting the development and function of NK cells." (PMID 40242752, 2025). "Here, we re-analyze a publicly available single-cell RNA sequencing (scRNA-seq) dataset of melanoma samples of patients subjected to ICT and identify a subset of macrophages overexpressing TREM2 and a subset of gammadelta T cells that are both overrepresented in the non-responding tumors." (PMID 33033253, 2020). "Moreover, GSEA indicated that the TREM2+ TAMs gene signature of ESCC was enriched in melanomas not responsive to anti-PD1 immunotherapy." (PMID 37187751, 2023). "Moreover, a recent study examined brain metastases from different cancer types (melanoma, breast, lung, ovarian, colorectal, and renal cancer) and revealed a cluster of TREM2+ macrophages (APOE, SPP1, C1QA-C, APOC1, FCGR3A), supporting a possible impact of TREM2 in the metastatic process." (PMID 35746551, 2022). "Experimental results demonstrated that PIc activates TREM2, thereby triggering the caspase 3/GSDME signaling pathway and inducing non-classical pyroptosis in melanoma cells, leading to significant inhibition of tumor growth." (PMID 40242752, 2025). "We focused on macrophages and identified TREM2+ TAMs specifically expressing TREM2, SPP1, APOE, C1QC, C1QB, and C1QA, which were significantly upregulated in melanomas not responsive to ICB therapy." (PMID 37187751, 2023). "Via targeting TREM2 expressed in TAMs, GB2 induces comprehensive tumor regression by administrating intravenously in mouse colon cancer models, as well as in a STINGlow mouse melanoma model, with no systemic toxicity." (PMID 39744236, 2025).
melanoma (continued). "CXCL9, CXCL10, PD-L1, CD86, IL-10, TREM2, GPNMB, IL-4l1 and FOLR2 markers showed widespread expression by most melanoma TAMs, with no definition of a particular macrophage subset, and regardless of whether the tumor was metastasizing or not." (PMID 40406129, 2025). "To investigate whether TREM2+ TAMs impact immunotherapy response, we re-analyzed scRNA-seq data of melanomas treated with ICB therapy and observed that TREM2+ TAMs were significantly enriched in melanomas not responsive to ICB therapy." (PMID 37187751, 2023).
breast cancer (19 papers, 2021 to 2025). A primary or metastatic malignant neoplasm involving the breast. "Similarly, TREM2 has been found to be highly expressed in tumor-associated macrophages (TAMs) in breast cancer." (PMID 39113887, 2024). "Importantly, ceramide induced TREM2+ TAMs are associated with T cell exhaustion in breast cancer." (PMID 38302493, 2024). "It has been reported that overexpressed TREM2 in breast cancer and colon cancer linking to poor prognosis." (PMID 39744236, 2025). "In breast cancer patients treated with anti-PD-1 therapy, TREM2+ TAMs are inversely correlated with T cell clonal expansion." (PMID 39113887, 2024). "On the other hand, depletion of TREM2+LAM suppressed tumor growth in breast cancer mouse model and improved anti-tumor immunity and immunotherapy efficacy." (PMID 38515213, 2024). "In immune checkpoint blockade‐resistant human breast cancer patients, a population of monocyte‐derived STAB+TREM2+ LAMs is expanded, and this subset is associated with the tumor stroma." (PMID 38426622, 2024). "Such work will help to develop a systemic understanding, from a metabolic perspective, of TREM2+ macrophages-CD8+ T cells crosstalk in breast cancer." (PMID 38302493, 2024). "Additional scRNA‐seq data from human breast cancer identifies a monocyte‐derived macrophage population expressing TREM2, SPP1, C1QA, and APOE." (PMID 38426622, 2024). "As therapies directed at specific macrophage subsets emerge, such as TREM2‐based therapies, identifying the presence of these macrophage subsets across the breast cancer subtypes will be important for developing the most effective therapeutic strategies." (PMID 38426622, 2024). "In breast cancer, a lipid-associated macrophage (LAM) bearing a TREM2 signature is described, which is usually associated with monocytic origin." (PMID 39104525, 2024). "Cell surface CH60 is also described to act as an agonist of various receptors, such as α3β1 integrin on breast cancer cells, TREM2 on microglia, and CD18 on macrophages." (PMID 36625202, 2023). "TREM2+ macrophages identified in the lungs of a mouse mammary tumor model demonstrated a gene expression profile akin to LAMs with positive enrichment for pathways associated with cholesterol and lipid metabolism." (PMID 36119485, 2022). "Similar inverse trends of TREM2 expression and overall survival have been documented with gastric, hepatic, colorectal, ovarian and breast cancers." (PMID 36031601, 2022). "Additionally, we need to understand the tumor cell intrinsic role of TREM2 in more types of solid cancers such as breast cancer." (PMID 36119485, 2022). "Notably, researchers have found TREM2+ LAMs at the marginal areas of breast cancer lung metastases, suggesting that TREM2+ LAMs may play a crucial role in promoting breast cancer lung metastasis." (PMID 40242752, 2025). "Finally, we asked whether our findings that TREM2+Mregs were enriched at the invasive margin of breast cancer lung metastasis models are also operative in human lung metastasis." (PMID 37756565, 2023). "As TREM2+ macrophages are infiltrating in nature during cancer development and transcriptionally proximal to CD14+ CCR2+ monocytes in breast cancer, they are concluded as HSC-derived recruited macrophages." (PMID 39104525, 2024). "TREM2 in macrophages has recently been shown to reduce CD8+ T cell anti-tumor activity and promotes an immunosuppressive environment in breast cancer, which correlates with poor outcomes." (PMID 39776914, 2024). "Flow cytometry analysis using a calibrated panel for the different myeloid populations showed that TREM2+ macrophages were specific to metastatic tissue in both EO771 and 4T1 breast cancer metastasis models." (PMID 37756565, 2023). "In the EMT6 breast cancer and the ID8 ovarian cancer model, eFc mAb treatment significantly reduced tumor growth and a number of TREM2+ macrophages." (PMID 35746551, 2022).
breast cancer (continued). "Using the 4T1 breast cancer model, we found TREM-1 and TREM-2 expression on MDSC and TAM and that sTREM-1 was elevated in tumor-bearing mice in multiple models and correlated with tumor volume." (PMID 35223446, 2021). "Interestingly, analysis of liver, lung, and lymph node metastases originating from ovarian serous and breast carcinoma and colorectal and lung adenocarcinoma by IHC demonstrate specific TREM2+ staining within the metastatic nodules and not in the surrounding normal tissue." (PMID 36119485, 2022). "A recent study of primary breast cancer tumors found that FOLR2+ tissue-resident macrophages are present in the tumor stroma, as opposed to TREM2+ macrophages that concentrate in tumor nests and margins." (PMID 37756565, 2023).